SATB2 (SATB homeobox 2)
Description:
Binds to DNA, at nuclear matrix- or scaffold-associated regions. Thought to recognize the sugar-phosphate structure of double-stranded DNA. Transcription factor controlling nuclear gene expression, by binding to matrix attachment regions (MARs) of DNA and inducing a local chromatin-loop remodeling. Acts as a docking site for several chromatin remodeling enzymes and also by recruiting corepressors (HDACs) or coactivators (HATs) directly to promoters and enhancers. Required for the initiation of the upper-layer neurons (UL1) specific genetic program and for the inactivation of deep-layer neurons (DL) and UL2 specific genes, probably by modulating BCL11B expression. Repressor of Ctip2 and regulatory determinant of corticocortical connections in the developing cerebral cortex. May play an important role in palate formation. Acts as a molecular node in a transcriptional network regulating skeletal development and osteoblast differentiation.
Synonyms: KIAA1034; FLJ21474; C2DELq32q33; DEL2Q32Q33; GLSS
Tractability: PROTAC: UniProt records ubiquitination sites on it; ubiquitination databases record sites on it; its protein half-life has been measured.
Target class: Enzyme; Oxidoreductase
Gene: Protein-coding gene on chromosome 2 (199,269,484 to 199,471,266, reverse strand). Ensembl gene ENSG00000119042.
Subcellular location: Nucleus matrix
Subcellular location (Human Protein Atlas): Nucleoplasm; Basal body; Centrosome; Cytosol
Pathways (Reactome):
Gene expression (Transcription): RUNX2 regulates osteoblast differentiation
Metabolism of proteins: SUMOylation of chromatin organization proteins
Gene Ontology:
Molecular function: DNA-binding transcription activator activity, RNA polymerase II-specific; protein binding; RNA polymerase II transcription regulatory region sequence-specific DNA binding; DNA-binding transcription factor activity, RNA polymerase II-specific; histone deacetylase binding; RNA polymerase II cis-regulatory region sequence-specific DNA binding; chromatin binding; DNA binding; DNA-binding transcription factor activity; sequence-specific DNA binding
Biological process: positive regulation of transcription by RNA polymerase II; chromatin remodeling; regulation of transcription by RNA polymerase II
Cellular component: nucleoplasm; chromatin; nucleus; histone deacetylase complex; nuclear lumen; nuclear matrix; transcription regulator complex
Genetic constraint (gnomAD): Loss-of-function variants: 1 observed, 61.67 expected, observed/expected ratio (o/e) 0.0162, 90% interval 0.005 to 0.077. The upper end of that interval is the gene's LOEUF score, 0.077, which puts it in group 1 of 6, group 1 being the genes least tolerant of losing a copy. Missense variants: 442 observed, 894.62 expected, observed/expected ratio (o/e) 0.49, 90% interval 0.46 to 0.54. Synonymous variants: 385 observed, 352.21 expected, observed/expected ratio (o/e) 1.09, 90% interval 1 to 1.19.
Gene-disease validity (ClinGen):
ClinGen rates the evidence that SATB2 causes each of these diseases.
SATB2 associated disorder (autosomal dominant): Definitive. A syndromic intellectual disability disorder that is characterized by significant neurodevelopmental disabilities with limited to absent speech, behavioral issues, and craniofacial anomalies.
Homologues: Orthologues: chimpanzee SATB2 (100% identical), dog SATB2 (99% identical), mouse Satb2 (99% identical), pig SATB2 (99% identical), rabbit SATB2 (99% identical), rat Satb2 (99% identical), macaque SATB2 (98% identical), guinea pig SATB2 (92% identical), tropical clawed frog satb2 (86% identical), zebrafish satb2 (75% identical), Drosophila melanogaster dve (23% identical), Caenorhabditis elegans dve-1 (16% identical). Paralogues in human: SATB1 (60% identical).
Diseases named in the same sentence as SATB2 in open-access papers:
SATB2 is named in the same sentence as 237 diseases in open-access papers, as found by Europe PMC text mining. Sharing a sentence is not in itself a finding about the gene and the disease. The quoted sentences say what the papers report.
colorectal cancer (60 papers, 2012 to 2025). A primary or metastatic malignant neoplasm that affects the colon or rectum. "Abnormal expression of special AT-rich sequence-binding protein 2 (SATB2) has been associated with the development and progression of several cancers, including esophageal cancer, colorectal cancer, and gastric cancer." (PMID 40636692, 2025). "SATB2, highly expressed in GI tissue, is associated with colorectal cancer and the regulation of GI inflammation." (PMID 39795948, 2024). "In intestinal epithelial-specific null mice with induced colitis, SATB2 deficiency promotes the disease development and colitis-associated colorectal cancer by influencing the intestinal luminal environment and gut flora (composition and infiltration)." (PMID 36671555, 2023). "Our study aimed to investigate SATB2 expression levels and the prognostic relevance of SATB2 loss in colorectal carcinoma (CRC), especially in comparison with CDX2, the standard marker of colorectal differentiation." (PMID 34944797, 2021). "SATB2 has been shown to suppress tumor progression in colorectal cancer, non‐small cell lung cancer and gastric cancer, and high SATB2 expression is associated with a favorable prognosis." (PMID 33124191, 2020). "Expression of the Special AT-rich sequence-binding protein 1 (SATB1) has been demonstrated to confer a worse prognosis in several tumour types, whereas its close homologue SATB2 is a proposed diagnostic and favourable prognostic marker for colorectal cancer." (PMID 25323550, 2014). "The results of this study demonstrate that SATB1 expression in colorectal cancer is significantly associated with beta-catenin overexpression, microsatellite stability and SATB2 expression." (PMID 22935204, 2012). "Special AT-rich sequence-binding protein 2 (SATB2) is a novel diagnostic marker of colorectal cancer (CRC), and loss of SATB2 has been linked to poor survival from the disease." (PMID 22333599, 2012). "CDX2 and SATB2 have been linked to colorectal cancer (CRC) progression." (PMID 39998677, 2025). "We have previously identified a higher rate of expression of CLDN18.2 in colitis-associated colorectal carcinomas with loss of intestinal markers such as SATB2, and the findings suggested colitis-associated colorectal carcinomas are promising candidates for CLDN18.2 targeted therapy." (PMID 39164422, 2025). "SATB2 is also a prognostic marker in UC-associated colorectal cancer." (PMID 35058554, 2022). "Due to the highly specific nuclear expression pattern in normal and malignant cells of the gastrointestinal tract, SATB2 protein expression was suggested as a clinically useful diagnostic biomarker for colorectal cancers, the third most commonly diagnosed cancer in the world." (PMID 22412953, 2012). "SATB2 has been shown to have tissue-specific expression, also related to some cancers, including colorectal cancer (CRC)." (PMID 40076993, 2025). "In colorectal cancer (CRC), reduced expression levels of CDX2 and SATB2 have been associated with poor differentiation and worse survival." (PMID 39998677, 2025). "Special AT‐rich sequence‐binding protein 2 (SATB2) is a commonly used clinical marker for colorectal cancer (CRC) diagnosis." (PMID 40636538, 2025). "For instance, certain markers are associated with specific cancers (e.g., NKX3.1 for prostate cancer or SATB2 for colorectal cancer)." (PMID 40916582, 2025). "Our data further support that CDH17, GPA33, and SATB2 in addition to CDX2 are all very sensitive markers for colorectal cancer metastases, and slightly more sensitive than CK20." (PMID 37349623, 2024). "This study demonstrated that upregulation of NEIL1 enhances colorectal cancer initiation through the formation of an RNA polymerase II transcriptional complex with SATB2 and cMyc, which drives COL17A1 expression leading to cancer-associated immunosuppression." (PMID 38779538, 2024).
colorectal cancer (continued). "SATB2 was found to be overexpressed in a variety of cancers, including colorectal cancer, hepatocellular carcinoma, and neuroendocrine tumors, and played an important role in the occurrence, development, and metastasis of cancers." (PMID 37107669, 2023). "SATB2 downregulation has been reported in sessile serrated pathway‐associated colorectal carcinomas, IBD associated colorectal carcinomas and dysplasias, and here we reveal that it also occurs in SSLs and MVHPs." (PMID 37036163, 2023). "For colorectal cancer, SATB2 was a relatively specific immunohistochemical marker for determining the origin of adenocarcinomas and distinguishing primary ovarian mucinous adenocarcinomas from colorectal metastases." (PMID 36581851, 2022). "It is well established that SATB2 acts as a negative regulator of EMT in colorectal cancer and non-small-cell lung carcinoma." (PMID 34074322, 2021). "miR-31-5p has been previously reported to regulate colorectal cancer progression by repressing SATB2." (PMID 34860243, 2021). "SATB2 is selectively expressed in the lower gastrointestinal tract mucosa and has been identified as a sensitive marker for colorectal cancer." (PMID 28969003, 2017). "Previous studies have shown 80%–96.8% diffuse positive or strong positive SATB2 staining in colorectal cancers." (PMID 28969003, 2017). "The combination of CDH17 and SATB2 had high sensitivity in colorectal cancer with medullary features." (PMID 28969003, 2017). "Low expression in other tumors has proved the high specificity of SATB2 in colorectal cancer, and it serves as an important marker to distinguish primary colorectal cancer from metastatic tumors." (PMID 28969003, 2017). "Recently, we reported that SATB2 inactivates ERK5 signaling to suppress the progression of colorectal cancer." (PMID 26701851, 2016). "SATB1 expression was increased, whereas SATB2 expression was reduced, in colorectal cancer tissues compared to control tissues." (PMID 26701851, 2016). "c-Myc was reduced by SATB2 expression, and exogenous expression of c-Myc in SATB2-expressing cells restored proliferation, colony formation and in vivo tumor growth of colorectal cancer cells." (PMID 26701851, 2016). "Recently, we reported that SATB2 inactivates MEK5/ERK5 signaling to suppress colorectal cancer progression." (PMID 26701851, 2016). "In this study, we examined the effects of SATB1 and SATB2 on the malignant characteristics of colorectal cancer cells." (PMID 26701851, 2016). "SATB2 mRNA levels were significantly reduced in human colorectal cancer specimens (n = 42) compared to the normal controls (n = 11)." (PMID 26701851, 2016). "Exogenous expression of SATB2 in colorectal cancer cells suppressed cell proliferation, colony formation and tumor proliferation in mice." (PMID 26701851, 2016). "SATB2 is a novel biomarker for colorectal cancer, where gene expression profiling has demonstrated association of transcriptional downregulation with metastasis and poor prognosis." (PMID 22412953, 2012). "A recent study showed that low expression of SATB2 was correlated with poor prognosis, tumor invasion, metastasis and Dukes' classification in colorectal cancer, further confirming the decreased level of SATB2 is a powerful prognostic factor in cancer." (PMID 22815795, 2012). "A recent study by Wang showed SATB2 protein was lower in primary colorectal cancer tissues than in their normal counterparts." (PMID 22815795, 2012). "Protein and mRNA expression of SATB2 was assessed in colorectal cancers using an array encompassing 60 primary tumors in duplicate." (PMID 22412953, 2012). "The results from this large, prospective cohort study of colorectal cancer demonstrate that SATB1 is expressed in a subset of colorectal carcinomas, and correlates with beta-catenin overexpression, microsatellite stable tumours and SATB2 expression." (PMID 22935204, 2012).
colorectal cancer (continued). "Additionally, we demonstrated that treatment with the demethylating agent azacytidine (AZA) restored SATB2 mRNA expression in a subset of colorectal cancer cell lines." (PMID 40636538, 2025). "In contrast, SATB2 expression was only seen in colorectal carcinomas." (PMID 40564811, 2025). "Similarly, we have previously reported the higher expression of SATB2 in breast, pancreatic, liver, and colorectal cancer." (PMID 38891096, 2024). "Recently, we and others observed reduced SATB2 expression in sessile serrated pathway‐associated colorectal carcinomas, inflammatory bowel disease (IBD) associated colorectal carcinomas and dysplasias, although SATB2 expression in SSLs, MVHPs, and TAs remained unclear." (PMID 37036163, 2023). "CDX2 downregulation in MSI‐H and CIMP‐H colorectal carcinomas may also be due to methylation of the promoter region, but it may occur later than SATB2 for unknown reasons." (PMID 37036163, 2023). "However, the distribution and prognostic relevance of SATB2 expression in colorectal carcinoma (CRC) have to be further elucidated." (PMID 34944797, 2021). "Indeed, SATB2 is documented to be a sensitive biomarker for colorectal carcinoma, pancreatic cancer and osteosarcoma." (PMID 32379794, 2020). "Then, we examined SATB2 mRNA levels in human colorectal cancer tissues using qRT-PCR analysis." (PMID 26701851, 2016). "Our results suggest that c-Myc may be a potential therapeutic target for colorectal cancers with high expression of SATB1 or low expression of SATB2." (PMID 26701851, 2016). "We next examined the effects of the exogenous expression of SATB2 on colorectal cancer cells." (PMID 26701851, 2016). "SATB1 and SATB2 expression were negatively correlated in colorectal cancer specimens." (PMID 26701851, 2016). "As an example, SATB2 expression was a favorable prognostic marker in colorectal cancer." (PMID 25326863, 2014). "Finally, the integration of CDX2 with molecular biomarkers such as MSI, RAS, BRAF, or SATB2 may lead to the development of comprehensive prognostic and predictive models, supporting a more personalized therapeutic approach in colorectal cancer." (PMID 41388313, 2025). "SATB2 is a DNA binding protein that specifically binds to the nuclear matrix attachment region regulates transcription of higher chromatin domain and is highly sensitive and specific to osteoblastic tumors, non-small cell lung cancer, breast cancer, and colorectal cancer." (PMID 37870753, 2023). "However, SATB2 has been shown to inhibit ERK5 activity in colorectal cancer cells." (PMID 34686672, 2021). "Furthermore, it remains to be elucidated, how frequently the loss of SATB2 occurs in comparison to the loss of CDX2 and whether SATB2 can identify distinct prognostic groups within these colorectal cancer subsets." (PMID 34944797, 2021). "As an example, the DNA-binding protein SATB2 was identified in the Human Protein Atlas as a potential novel diagnostic marker for colorectal cancer and in an extended study including more than 2,400 tumors, SATB2 was found to be both a sensitive and highly specific marker for colorectal cancer." (PMID 22971420, 2012). "This immunoprofile differs from that of primary colorectal cancer, which generally shows strong CDX2 and SATB2 positivity." (PMID 41159019, 2025). "For example, upregulated lncRNA LINC00691 was a poor prognostic predictor for patients with lung cancer, and through modulation of SATB2, the downregulated lncRNA SATB2-AS1 inhibits tumor metastasis in colorectal cancer." (PMID 36891153, 2023). "Specifically, lncRNA SATB2-AS1was reported to inhibit colorectal cancer (CRC) cell metastasis and regulate the immune response of CRC by cis-activating SATB2." (PMID 35568824, 2022).
colorectal cancer (continued). "At the same time, CDX-2 (+) and SATB2 (+) was discussed as combination marker to discriminate colorectal carcinoma from other primary carcinoma, and 19% of gastrointestinal adenocarcinoma with CK7 (+) /CDX-2 (+) /SATB2 (+) showed primary colorectal cancer." (PMID 36463302, 2022). "We first compared the expression of SATB2 in human normal colon epithelial cells (CRL-1831) and colorectal cancer (CRC) cell lines (Colon-320, HT-29 and HCT-116) by qRT-PCR, Western blot analysis and immunocytochemistry (ICC)." (PMID 28887549, 2017). "The results elucidate the importance of SATB1 and SATB2 in understanding oncogenic c-Myc-induced colorectal tumorigenesis, making SATB1 a promising therapeutic target for colorectal cancer." (PMID 26701851, 2016). "In this report, we examined the effects of SATB2 expression and SATB1 knockdown in different colorectal cancer cell lines." (PMID 26701851, 2016). "Further, statins treatment is known to downregulate SATB1 in colorectal cancer cells but the effect on its homolog SATB2 is not known." (PMID 40177244, 2025). "Histopathology and immunohistochemistry (CK7, CK20, CDX2, SATB2, Arginase-1) confirmed that the intestinal lesions were metastases from gastric cancer rather than synchronous primary colorectal cancers." (PMID 41159019, 2025). "A cohort study observed a strong negative correlation between microsatellite instability in colorectal cancer and SATB2 expression levels." (PMID 39440054, 2024). "Notably, recent findings have revealed that SATB2 AS1, an antisense transcript of the tumor suppressor SATB2, is downregulated in colorectal cancer." (PMID 39553554, 2024). "Antisense transcript of SATB2 promoted the expression of SATB2 by recruiting p300 to the promoter region and consequently inhibited snail transcription, thereby suppressed EMT and aggressiveness of colorectal carcinoma." (PMID 34480024, 2021). "Thus, decreased miR-34a expression contributes to a miR-449a-mediated negative feedback loop to maintain low levels of miR-449a/34a and high levels of SATB2, Sirt1, HDAC1 and DNMT3a in colorectal cancer cells." (PMID 29254139, 2017). "Strikingly, we also evaluated SATB2 expression in CRC and found that SATB2 was more abundantly expressed in non-cancerous mucosa compared to colorectal cancer tissues (p<0.001)." (PMID 24971456, 2014). "Very strong immunoreactivity for SATB2 was observed in colorectal mucosa as well as in colorectal cancer (data not shown)." (PMID 25326863, 2014). "Future studies are needed to elucidate the potential mechanisms by which SATB1 affects colorectal cancer progression, not least its potential synergistic or antagonostic effects with SATB2." (PMID 22935204, 2012). "SATB2, a DNA-binding protein involved in transcriptional regulation and chromatin remodeling, has been established as a sensitive marker for colorectal carcinoma, although it is not specific since positivity can be seen in gastrointestinal and pancreatobiliary adenocarcinoma." (PMID 41463263, 2025). "Interestingly, six SBAs (two CD-SBAs and four Spo-SBAs) displayed a full colorectal carcinoma (CRC)-like immunoprofile (CK7−/CK20+/CDX2+/AMACR+/SATB2+); none of them was a CrD-SBA." (PMID 33228145, 2020). "Kaplan-Meier estimates of colorectal cancer-specific survival according to combination of SATB1 and SATB2 expression showed that SATB1-negative/SATB2-positive and SATB1-negative/SATB2-negative groups have the better survival time." (PMID 24971456, 2014).